MCL1 (MCL1 apoptosis regulator, BCL2 family member)
Diseases named in the same sentence as MCL1 in open-access papers (continued):
Sharing a sentence is not in itself a finding about the gene and the disease.
cancer (continued). "The level of Mcl-1/Mule complex would determine the sensitivity of cancer cells to apoptosis." (PMID 22078414, 2011). "This work establishes that, in HER2-overexpressing tumors, it is necessary, and maybe sufficient, to therapeutically impact on the Mcl-1/Bim balance for efficient induction of cancer cell death." (PMID 21899728, 2011). "Therefore, our data indicated that high susceptibility to TRAIL of metastatic cancer cells is associated with up-regulation of DR5 and concurrent down-regulation of c-FLIP and Mcl-1 by TRAIL treatment." (PMID 21513580, 2011). "Therefore, we analysed the expression levels of three anti-apoptotic Bcl-2 family members, Bcl-2, Bcl-XL and Mcl-1, in all five cancer cell lines." (PMID 21708043, 2011). "As a pro-survival protein, high levels of Mcl-1 were detected in human malignancies such as in prostate, breast, colon and lung, and appear to be a factor in the resistance of some cancer types to conventional cancer therapies." (PMID 22046442, 2011). "Therefore, to bypass cancer cell survival with a Bcl-2 antagonist, neutralizing Mcl-1 appears to be critical in certain tumour environments." (PMID 19079626, 2008). "Our results suggest that the inability of cells with FBW7 point mutations and truncations to suppress c-Myc and Mcl-1 may contribute to chemotherapy resistance in cancers lacking the sixth WD domain." (PMID 40338031, 2025). "However, resistance may emerge in cancers with elevated Mcl-1 expression, where sequestration of pro-apoptotic proteins such as BIM, PUMA, or NOXA prevents apoptosis." (PMID 41149606, 2025). "Finally, we hypothesized that inactivation of c-Myc and Mcl-1 would sensitize Gln-K604-null cancers to chemotherapy." (PMID 40338031, 2025). "Myeloid cell leukaemia-1 (Mcl-1) is another member of the Bcl-2 family that may inhibit apoptosis in senescent cells, Mcl-1 is upregulated in senescent cancer cells and the Mcl-1 inhibitor S63845 eliminates senescent cancer cells more effectively than navitoclax." (PMID 40554265, 2025). "In addition, MCL-1, which is an anti-apoptotic (BCL2 family) protein and an FBW7 substrate, is frequently amplified or stabilized due to loss-of-function FBW7 mutations in cancer." (PMID 39851497, 2025). "Furthermore, the expression of Mcl-1 markedly decreases in cancer cells after IMQ treatment." (PMID 39272918, 2024). "Hence, targeting and studying the role of Mcl-1 in cancer cells may aid in the development of cancer therapies." (PMID 39272918, 2024). "However, cancer cells may develop resistance to BH3 mimetics by upregulating other antiapoptotic proteins like Mcl‐1." (PMID 39239068, 2024). "Additionally, cancer cells may exhibit intrinsic and acquired resistance to MCL1 inhibition that could reduce the clinical efficacy of MCL1 inhibitors." (PMID 39802137, 2024). "Various studies have proven that the levels of this prosurvival protein, taken into account together with clinicopathological characteristics, have prognostic value for patients with cancer, and MCL1 may be a prognostic biomarker for patients with certain types of cancer." (PMID 38256213, 2024). "Therefore, using MCL1 inhibitors in combination with ICIs for these cancers may improve outcomes and kill cancer cells, through the MCL1 inhibitor’s direct killing effects on tumor cells and indirect effects on MDSCs." (PMID 38459020, 2024). "We hypothesize that NSC260594 will inhibit Mcl-1 and induce cancer cell apoptosis in TNBCs." (PMID 37481672, 2023). "Interestingly, MCl1 in cancer cells regulates lipid metabolism through a functional gain." (PMID 37842232, 2023). "However existing MCL-1 inhibitors lack sufficient potency and specificity for cancer treatment." (PMID 38027013, 2023). "Therefore, it is well-established that Mcl-1 plays critical roles in venetoclax resistance, and combination treatment of venetoclax with Mcl-1 inhibitors induces synergistic anti-tumor activity and eradicates venetoclax-resistant cancers." (PMID 36658493, 2023).
cancer (continued). "Thus, TRIP12/FBW7/MCL-1 axis is an important determinant of Taxol response in cancer cells." (PMID 36672454, 2023). "Thus, we hypothesized that NSC260594 treatment could overcome drug resistance not only through Mcl-1 inhibition but also through cancer stem cells suppression." (PMID 37481672, 2023). "Based on the fact that pro‐survival BCL‐2 proteins are frequently linked with cancer progression and chemotherapy resistance, a number of highly specific BH3‐mimetic compounds have been developed, including pan‐BCL‐2‐targeting ABT‐737/ABT‐263, MCL‐1‐targeting S63845, and BCL‐2‐targeting ABT‐199." (PMID 37846472, 2023). "Because Mcl-1 has a very short half-life (usually referred to as 1 h) when compared to other antiapoptotic proteins, it may be possible to battle these tumors by sensitizing Mcl-1-dependent cancer cells to chemotherapy-induced apoptosis when Mcl-1 is inhibited." (PMID 35745769, 2022). "Indeed, Mcl-1 upregulation in response to proteasome inhibitors has been regarded as a major factor to prevent apoptotic cell death in cancer cells, and its targeted downregulation or pharmacological inhibition enhances the cell death induced by proteasome inhibitors." (PMID 36045907, 2022). "Although the role of MCL1 in regulating apoptosis is well established, emerging data highlight additional functions related to autophagy, mitochondrial respiration, and DNA damage, which may also contribute to chemoresistance and cancer progression." (PMID 35042842, 2022). "Moreover, Bcl-xL and Mcl-1 are key targets in various cancers, such as hematological cancers." (PMID 35693733, 2022). "The upregulated Mcl1 can also inhibit autophagy, which could augment apoptosis in cancer cells." (PMID 36267274, 2022). "Therefore, it was guessed that whether LINC00641 performed as a ceRNA to mediate miR-320d/MCL1 axis and taking on effect in stimulating cancer in OS." (PMID 35266447, 2022). "Consequently, induced Mcl1 expression can potently enhance drug resistance in cancer cells treated with BH3-mimetics and Mcl1 inhibitors are showing their true potential in over-coming this when utilized in combined- therapeutic treatments, in pre-clinical studies." (PMID 34753495, 2021). "Also, MCL1 is being studied as a target for cancer patient treatment in small cell lung cancer." (PMID 33649335, 2021). "Therefore, whether and how MCL1-promoted mitochondrial fusion is involved in drug resistance in obese patients with cancer deserves further investigation, and this process can serve as a therapeutic target for the treatment of cancers." (PMID 34156978, 2021). "In the following sections, we summarize the current discoveries of direct and selective inhibitors of MCL-1, including the current status and future applications of these small molecule inhibitors, as well as their use alone and in combination to treat a variety of cancers." (PMID 33883020, 2021). "It is documented that members of the Bcl‐2 family, including Bcl‐2 and Mcl‐1, regulate apoptosis and caspase activation by regulating the mitochondrial membrane integrity, and the decline of the expression levels of Bcl‐2 members contributes to apoptosis induced by some anti‐cancer agents." (PMID 34318593, 2021). "Moreover, lucanthone upregulated DR5 and downregulated DUB3 and Mcl-1 in both cancer cells." (PMID 35008442, 2021). "Indeed, Mcl-1 overexpression was related to poor prognosis in many cancer types." (PMID 33919902, 2021). "In response to various extracellular stimuli including cytokines and growth factors, Mcl-1 expression levels are thoroughly controlled via multiple processes such as transcriptional, posttranscriptional, and posttranslational regulation, thereby determining cancer cell survival or death." (PMID 34391437, 2021). "Importantly, the ability of DMC to impede MCL-1 expression in some cancers (e.g., leukemia) may represent a promising approach to overcome resistance to ABT-737." (PMID 34356673, 2021).
cancer (continued). "Notably, the current literature on the role Mcl-1 in cancer mainly focuses on tumor cells." (PMID 34336857, 2021). "Interestingly, an independent study aiming at elucidating the molecular basis of immune resistance in cancer cells showed that NANOG-mediated/HDAC1-driven epigenetic silencing of TRIM17 resulted in stabilization of MCL1 and subsequent resistance to apoptosis in immune-edited tumor cells." (PMID 34069831, 2021). "Many small-molecular inhibitors could be tested with the goal of MCL1 inhibition in cancer cells." (PMID 34156978, 2021). "Consequently, from a therapeutic standpoint, Mcl1 expression and regulation have taken on increasing levels of importance, particularly from the contribution they make in offering drug resistance to several cancer therapeutics." (PMID 34753495, 2021). "From these three groups, the BAX (pro-apoptotic) and Bcl-2, Bcl-xL or Mcl1 (anti-apoptotic) proteins have gained the most attention over the recent decades, based on their deregulated expression, significance in the development of a number of cancers and their responsiveness to therapeutics." (PMID 34753495, 2021). "However, inhibitors of anti-apoptotic factors such as Mcl-1, already in development in cancer therapy, may restore an appropriate apoptotic pathway in PMN and disrupt the intracellular niche for S. aureus." (PMID 33262756, 2020). "Besides, MCL1 has recently been regarded as a promising target for cancer treatment." (PMID 33126914, 2020). "Therefore, we hypothesized that DYRK1A suppression would sensitize cancer cells to Bcl-2 inhibitor treatment by suppressing Mcl-1 expression." (PMID 32587776, 2020). "The evidence suggested Mcl-1 might be a promising therapeutic target for cancer treatment." (PMID 32081857, 2020). "Anti-apoptotic inhibitors such as A-1331852 (BCL-xL selective), ABT-199 (BCL-2 selective), S63845 (MCL-1 selective) among others that are now evaluated in the clinic, can be used as single agents or especially in combination with other therapies to enhance cancer elimination." (PMID 32801295, 2020). "Therefore, MCL1 is considered as a potential target for cancer treatment." (PMID 33126914, 2020). "In addition, our discovery of the role of MCL-1 as a mitophagy mediator and the ability of MCL-1 inhibitors to induce mitophagy may help to consider this function of the anti-apoptotic protein when designing and evaluating cancer therapies that target MCL-1." (PMID 33184293, 2020). "This higher efficacy might be explained by the E-antibiotics impacting both crucial short-lived proteins such as c-MYC and MCL-1 involved in stimulating cancer proliferation and survival, as well as mitoribosomes whose mt-r-proteins are translated by 80S ribosomes." (PMID 32151059, 2020). "However, MCL1 can promote drug resistance and overall cancer cell survival." (PMID 30796196, 2019). "As Mcl-1 was demonstrated to control for survival and progression of cancer, these data might be beneficial for highlighting RT as a novel lead compound with supportive information to be further developed for targeted anti-cancer approaches." (PMID 31117253, 2019). "One is A-1210477, which could direct target the anti-apoptotic protein MCL1 and induce apoptosis, and the other is Vincristine, which is a common chemotherapy drug used in many types of cancers, inducing cancer cell death through a microtubule polymerization mechanism." (PMID 31406154, 2019). "Moreover, MCL1 inhibition potentiates the in vivo efficacy of PARP inhibition (PARPi), underscoring the therapeutic potential of this combination for treatment of BRCA1-mutated cancer patients with poor response to PARPi monotherapy." (PMID 30674894, 2019). "The upregulation of antiapoptotic proteins of the BCL-2 family following LKB1 loss suggests that LKB1-defective cancers could be sensitive to BH3 mimetics, particularly to MCL1 inhibitors, some of which—such as AZD5991—are currently in clinical trials for the treatment of hematological malignancies." (PMID 31781355, 2019).
cancer (continued). "Our study demonstrates that MCL1 inhibition considerably enhances response of BRCA1-mutated TNBC to the clinical PARPi olaparib and suggests that this combination should be prioritized for clinical evaluation, especially in BRCA1-mutated cancer patients with poor response to PARPi monotherapy." (PMID 30674894, 2019). "However, MCL1 can promote resistance and overall cancer cell survival despite these therapies." (PMID 30796196, 2019). "Thus bCAFs favor both MCL-1 mRNA expression and protein stability in cancer cells." (PMID 30631150, 2019). "Thus, Mcl-1 has emerged as a promising target for cancer treatment." (PMID 29866132, 2018). "Thus, holotoxin A1 might be very effective for killing cancer cells that overexpress Bcl-xL and Mcl-1." (PMID 29642569, 2018). "Furthermore, since Mcl-1 is highly expressed in several cancers, our results support the notion that the increased levels of Mcl-1 may block BOK pro-apoptotic activity by interacting and sequestering BOK away from localizing to the mitochondria." (PMID 29156771, 2017). "Therefore, MCL-1 is a high-priority therapeutic target for cancer treatment." (PMID 27086916, 2017). "The effect of hinokiflavone on MCL1 splicing and its ability to induce cell cycle arrest and/or apoptosis, raise the possibility that either hinokiflavone itself, or a synthetic derivative thereof, could be developed in future as a novel cancer therapeutic." (PMID 28884683, 2017). "Secondly, it was described that some cardenolides and bufadienolides downregulate, in several cancer cell lines, one anti-apoptotic protein, Mcl-1, a Bcl-2 family member responsible for cancer cell resistance, and consequently could be considered as an essential and universal target of CGs." (PMID 29117117, 2017). "In addition to BCL2 and BCL‐XL, MCL1 is an important target for cancer therapy." (PMID 28548464, 2017). "Therefore, the MCL-1 could be considered as an important target for the cancer therapy, and knockdown of MCL-1 has been reported to increase the anti-tumor effect of chemotherapeutic drugs including cisplatin." (PMID 28423543, 2017). "Taken together, our data present an intriguing insight into the relevance of neutrophils in cancer cell sensitivity to anticancer agents and suggest that pharmacological modulation, for example with anti-Mcl-1 compounds, could be used to enhance the effect of cytotoxic agents in patients with NHL." (PMID 29069828, 2017). "In the current study, we demonstrate that targeting Mcl-1 during senescence-inducing doxorubicin treatment in otherwise senescence-resistant cells causes activation of the ROS-dependent DNA damage response (DDR), which is critical for the induction of senescence in cancer." (PMID 28423654, 2017). "Furthermore, chemotherapy or chronic BCL-2 inhibition in tumors initially sensitive to venetoclax may also lead to compensatory upregulation of MCL-1 and consequent emergence of drug-refractory cancer cells." (PMID 29269870, 2017). "Thus reducing carbohydrate intake may represent a safe way to decrease Mcl-1 expression and to sensitize tumor cells to anti-cancer therapeutics." (PMID 27689327, 2016). "The genes MAPK3, HMGB1, HMGA1, PIK3CA, and MCL1 are genes known to stimulate cellular growth; however, contrary to what is normally reported in humans, in the present study these genes were shown to be consistently expressed at lower levels in malignant tumors." (PMID 27657059, 2016). "The combination of a BH3 mimetic with taxol might therefore achieve an improved therapeutic index against proliferating cancer cells, particularly those in which the response to mitotic stress is suppressed by overexpression of Mcl-1 or another inhibitor of caspase activation." (PMID 25761368, 2015). "Therefore, the use of Mcl-1 targeting agents in combination with BH3-mimetics could constitute an interesting therapeutic strategy in these types of cancers." (PMID 25627260, 2015).
cancer (continued). "However, there are some cancers that cannot be treated with these Bcl-2 inhibitors, in which the upregulation of Mcl-1 may play a key role." (PMID 26056043, 2015). "Hence, GA may be more potent and optimal than conventional proteasome inhibitor (eg., bortezomib) to kill cancer cells considering the important role of Mcl-1 in cell survival." (PMID 25853502, 2015). "Therefore, detection of Mcl-1 levels in tumor tissues may be a valuable strategy to identify cancer patients most probably respond to dinaciclib." (PMID 25962959, 2015). "Furthermore we present a novel mechanism by which GX15-070 counteracts Mcl-1 expression which may lay a foundation for a novel target in cancer therapy." (PMID 26008975, 2015). "Mcl-1 became one of the most investigated members of the Bcl-2 family but the poor availability of specific Bcl-2 family inhibitors specifically targeting this protein hindered improved treatment protocols especially of Mcl-1 overexpressing and chemoresistant cancer types." (PMID 26068790, 2015). "Notably, Mcl-1 is responsible for the resistance to the new generation of BH3 mimetic cancer therapies, including ABT-737 and ABT-263, which bind to the anti-apoptotic proteins Bcl-2, Bcl-xL and Bcl-w to disrupt their interaction with the pro-apoptotic Bcl-2 family members." (PMID 24814761, 2014). "Therefore, a better understanding the role of this regulatory molecule in Mcl-1 expression in cancers may allow for the development of rational therapeutics that control Mcl-1 levels." (PMID 24529193, 2014). "Furthermore, overexpression of Mcl-1 is correlated with shorter survival of cancer patients." (PMID 23594563, 2013). "However, the role of Mcl-1 in autophagic response of cancer cells is unclear." (PMID 24025188, 2013). "Hence, these findings suggest that Mcl-1 overexpression may function as an additional survival mechanism to protect cancer cells against conventional therapies." (PMID 23680104, 2013). "Redundancy is reflected in miR-29 and miR-101 regulation of the anti-apoptotic MCL-1, indicating that this is an important pathway in cancer and highlighting the potential for future AD research, given that molecules involved in cell survival could play an important role in neurodegeneration." (PMID 23335942, 2012). "Hence, the cumulative evidence to date suggests that Mcl-1 overexpression may function as an additional survival mechanism that protects cancer cells against conventional therapies." (PMID 23171055, 2012). "Collectively, results suggested that glucose metabolism of tumor cells relies on mTOR activity and 4E-BP1 phosphorylation to sustain Mcl-1 protein translation, and that diminished expression of Mcl-1 through the disruption of aerobic glycolysis may sensitize cancer cells to apoptosis." (PMID 22680924, 2012). "Thus, using combined treatment with proteasome inhibitors and Mcl-1 antagonists may provide an effective and safe strategy for cancer therapy." (PMID 22078414, 2011). "However, considering the characteristics of SP cells for cancer-initiating ability, the apoptosis-related molecules among these genes (MCL-1, ANKRD11, PHLDA3 and APOL1) might have roles in the proliferation of SP cells." (PMID 19826427, 2009). "Therefore, MCL-1 has been suggested as a potential new therapeutic target for many types of cancer." (PMID 18789152, 2008). "Other BH3 mimetics targeting MCL-1 and BCL-XL are also in various stages of preclinical and clinical development and have been shown to have activity in a myriad of cancer types including highly chemoresistant solid tumors." (PMID 41507122, 2026).